IL4 (interleukin 4)
Diseases named in the same sentence as IL4 in open-access papers (continued):
Sharing a sentence is not in itself a finding about the gene and the disease.
Miscarriage (18 papers, 2012 to 2025). A pregnancy that ends at a stage in which the fetus is incapable of surviving on its own, defined as the spontaneous loss of a fetus before the 22th week of pregnancy. "IL-2/IFN-γ and IL-4/IL-10 are secreted by Th1 and Th2 lymphocytes, respectively; therefore, the results from the previous studies support a shift from Th1 to Th2 signaling events during implantation; and preventing this shift is associated with miscarriage." (PMID 24926365, 2014). "In the present study, the levels of different subsets of NKT-like cells and IFN-γ, IL-2, IL-4, and IL-17 cytokines were characterized and evaluated as potential immunological parameters that could be used for the prediction of pregnancy loss in women who had unexplained recurrent miscarriage (URM)." (PMID 34849421, 2021). "We observed significantly higher levels of Il-4 and Il-5 (which belong to Th2 cytokines) in women with miscarriage." (PMID 34444287, 2021). "Whitcomb tested the serum of women 10 days before miscarriage, and found low levels of several pro-inflammatory cytokines, IL-1β, IL-4, IL-6, IFN-γ and TNF- α, which confirms our findings." (PMID 34300281, 2021). "IL-4 is an archetypal cytokine involved in TH2-mediated adaptive immunity and during pregnancy is thought to help reduce the risk of miscarriage." (PMID 30134952, 2018). "They induce miscarriage in mice, which can be reversed by inhibitors of the Th1 cytokines or by administering the anti-inflammatory IL-10 and Th2 cytokine IL-4." (PMID 26335138, 2015). "In this study, we assessed the levels of different subsets of NKT-like cells and specific related Th1(IFN-γ, IL-2)/Th2 (IL-4) and Th17 (IL-17) cytokines, and their ability to predict recurrent miscarriage in women who have experienced URM, by comparing different case and control groups." (PMID 34849421, 2021). "Moreover, in normal pregnancy, Tim-3+PD-1+ CD8+ T cells, the number of which was more than that in miscarriage, produced higher levels of IL-4 and IL-10 but lower levels of IFN-γ and TNF-α." (PMID 25950468, 2015). "In cases of miscarriage, the expression of B7-2 was found to be highly upregulated at the fetomaternal interface and this was associated with high levels of Th1 cytokines (IL-2 and IFN-gamma) and low levels of Th2 cytokines (IL-4 and IL-10)." (PMID 25189405, 2014). "Studies have shown that when miscarriage occurs, maternal expression of Th1-type cytokines such as TNF-α is elevated, whereas the expression of Th2-type cytokines such as IL-4 was downregulated." (PMID 39351087, 2024). "They showed that the concentrations of Il-5 as well as Il-4 or TNF-β are undetectable in sera of both healthy pregnant women and those with recurrent miscarriage." (PMID 34444287, 2021). "We showed a positive correlation of Il-4 with both INF-γ as well as with Il-1β and TNF-α in the case of miscarriage." (PMID 34444287, 2021). "Studies done with lymphocytes isolated from women with recurrent miscarriage indicate that dydrogesterone inhibits the production of INF-γ, TNFα, IL-4, and IL-6 modifying the Th1/Th2 ratio." (PMID 26446923, 2015). "Prior investigations did not make comparative measurements of IL-17 production by decidual CD4+ T cells in normal pregnancy and miscarriages and none identified Th17 subpopulations able to produce IL-4 or IFN-γ together with IL-17 (Th17/Th2 and Th17/Th1, respectively)." (PMID 26798325, 2016). "Our findings differed from other studies that showed plasma IL-4 concentrations in early pregnancy were reduced in women with recurrent miscarriages compared to normal pregnancy, but levels measured in the miscarriage cohort occurred at the time of miscarriage diagnosis and not prospectively." (PMID 34441875, 2021).
renal cell carcinoma (18 papers, 2002 to 2024). "For cancer-type subgroup analysis, the susceptibility of renal cell carcinoma was observed to be associated with the polymorphism of IL-4-590C/T." (PMID 31871935, 2019). "Subgroup analysis based on types of cancer demonstrated the IL-4-590C/T variant achieved a lower risk in renal cell cancer (CC vs. TT: P=0.046, OR = 0.640, 95% CI: 0.412–0.993)." (PMID 31871935, 2019). "Our results demonstrated that IL-4-590C/T polymorphism had a lower risk for renal cell cancer (CC vs. TT: P=0.046, OR = 0.640, 95% CI: 0.412–0.993)." (PMID 31871935, 2019). "And IL-4-590C/T polymorphism may have a protective effect on renal cell cancer." (PMID 31871935, 2019). "In renal cell carcinoma, IL-4 and TNF-α synergistically induced apoptosis and cytokine production in vitro, promoting the recruitment of different immune effector cells." (PMID 28005163, 2017). "Vascular endothelial growth factor C (VEGF-C), interleukin-4 (IL-4), colony-stimulating factor 2 (CSF2), prospero homeobox 1 (PROX1), and TEK receptor Tyrosine Kinase (TEK) is significantly associated with lymph node metastasis in renal cell carcinoma (RCC)." (PMID 38167072, 2024). "The IL-4/GM-CSF (granulocyte–macrophage colony-stimulating factor) procedure for culturing blood monocyte-derived DCs was applied to cells from healthy donors and patients (17 with breast, 7 with colorectal and 10 with renal cell carcinoma)." (PMID 15987427, 2005). "In addition, CXCL5, IL4 may be involved in the regulation of the immune microenvironment in renal cell carcinoma." (PMID 34187413, 2021). "In the model of BALB/c mice with renal cell carcinoma (RCC), circulating levels of M2-like markers and pro-angiogenic cytokines, including IL-4, IL-10, IL-13, and VEGF-A, were reduced in endostatin-treated animals in comparison with non-treated control." (PMID 34209679, 2021). "For instance, IL-4 and TNF-α exert synergistic effects on the PD-L1 induction in renal cell carcinoma (RCC) by activating signaling molecules, including NF-κB, IκB, and STAT6." (PMID 34088360, 2021). "In a phase II trial of advanced renal cell carcinoma where 49 patients were treated with subcutaneous injection of IL-4 at 5 mcg/kg per day for 28 days, no complete or partial responses were observed." (PMID 37455828, 2023).
renal fibrosis (18 papers, 2019 to 2026). A final common manifestation of a wide variety of chronic kidney diseases characterized by glomerulosclerosis and tubulointerstitial fibrosis. "The frequency of IL-4-producing cells in peripheral blood was higher in a mouse model of CKD, and IL-4 deficiency resulted in Myd88-mediated renal fibrosis in a mouse experiment." (PMID 39451595, 2024). "A mouse model of unilateral ureteral ligation-induced chronic kidney disease has demonstrated that the frequency of IL-4-producing cells was increased in the peripheral blood, and Il4-deficient mice exhibited impaired renal fibrosis mediated by the Myd88 signaling pathway." (PMID 36362231, 2022). "Besides that, CD226 deficiency on Tregs exacerbated renal fibrosis in the UUO model by upregulating Th2-related cytokines like IL-4." (PMID 34616308, 2021). "We also evaluate the therapeutic rationale for targeting IL-4 signaling and highlight candidate molecular targets to mitigate renal fibrosis." (PMID 41787321, 2026). "ILC2/IL‐4 or IL‐13/TGF‐β1 exacerbate renal fibrosis in DKD, which is defined by proteinuria and eGFR." (PMID 40801800, 2025). "This decrease in adiponectin levels enhances the expression of transforming growth factor-beta (TGF-β) and interleukin-4 (IL-4) in the glomerulus, thereby promoting renal fibrosis." (PMID 39763063, 2025). "The NKT cell/IL-4 signalling pathway stimulates activation of bone marrow-derived fibroblasts and conversion of M2 macrophages to myofibroblasts in renal fibrosis." (PMID 39445007, 2024). "Furthermore, the suppression of renal fibrosis in TG2-knockout mice was abolished by transplantation of wild-type bone marrow or by renal subcapsular injection of IL4-treated macrophages derived from bone marrow of wild-type, but not TG2 knockout." (PMID 36864028, 2023). "Indeed, along with the reduction of glomerular fibronectin in HFD-fed mice, AdipoRon attenuated the glomerular expression of TGFβ and renal expression of IL-4, both known to promote renal fibrosis." (PMID 33987714, 2021). "The remaining signalling pathways mediating renal fibrosis are STING/TBK1, IL-4Ra/STAT6, Jmjd3/IRF4, STAT6/PPARα, SETD7, NKT/IL-4, BRP-39, STAT-1/TREM-1, MMP-9/Akt, adiponectin/APK, and JAK3/STAT6." (PMID 39445007, 2024). "Q-PCR indicated a significant reduction in the expression of renal fibrosis-related genes (fn-1, αSMA, Col1a1, Col3a1, Ctgf, fsp1, KIM) and inflammatory cytokines (Tgfα, Tgfβ, Il-1b, Il-4, Il-6, CD44, CD68) in the kidney of the acetate-treatment group." (PMID 36922584, 2023). "As reported in recent literature, CCL-5 and IL-4 were modulated by NGAL produced from macrophages and were proved to play a critical role in renal fibrosis." (PMID 35585990, 2022). "Our study found that the secretion of the Th2 cytokines (IL-4, IL-13) and the upregulation of TGF-β1 were the key factors leading to renal fibrosis in DKD." (PMID 31355294, 2019). "The ILC2-related Th2 cytokines (IL-4, IL-13) promote the expression of TGF-β1, leading to renal fibrosis via Smads and MAPKS signaling pathways." (PMID 31355294, 2019). "Here, we show that chimeric antigen receptor-modified M2 macrophages (CAR-M2) targeting FAP and secreting interleukin (IL)-4 are delivered via an injectable HAMA-CS hydrogel beneath the renal subcapsule and attenuate renal fibrosis while promoting renal revascularization." (PMID 41887221, 2026). "Hypoxia‐inducible factor‐prolyl hydroxylase (HIF‐PHD) inhibitors alleviated renal fibrosis through reduced phosphorylation of p38MAPK in ILC2s; thus, M2 polarisation followed by IL‐4/IL‐5/IL‐13 production was decreased, suggesting the pathogenesis role of ILC2/cytokines/M2 in renal fibrosis." (PMID 40801800, 2025). "At least, MST1/2 inhibition could reduce the IL-4+IL-13-induced activation of STAT6 and MEK/ERK in macrophage independent and dependent of YAP, and MST1/2 inhibition impaired M2 polarization and renal fibrosis." (PMID 38250155, 2024).
renal fibrosis (continued). "So, it could be inferred that H2S alleviates renal fibrosis in response to UUO by suppressing macrophage infiltration through inhibition of NLRP3 inflammasome via NF-κB and IL-4/STAT6 signaling pathways, which needed to be further proven 57-59." (PMID 33110394, 2020). "Although CD8+ T cell depletion intensifies renal fibrosis by decreasing IFN-γ and increasing IL-4 in the kidneys, the change and role of CD8 T cell populations following environmental changes during renal fibrosis are largely unknown." (PMID 32921633, 2020). "Interestingly, renal fibrosis and inflammatory mediators, including TGF-β, angiotensin II, PDGF-B, and IL-4 and IL-13, could upregulate the expression of periostin." (PMID 34992536, 2021). "Besides, it has been reported that in IL-4 and IL-13-treated HK-2 cells, the JAK-STAT6 signaling pathway was sufficiently activated to promote EMT, mesangial cell proliferation, ECM deposition, and foot cell damage, eventually leading to renal fibrosis." (PMID 31355294, 2019). "However, when IL-4 signaling persists during chronic injury, it may contribute to maladaptive remodeling, including activation of profibrotic myeloid and stromal programs and accumulation of extracellular matrix (ECM), thereby promoting renal fibrosis." (PMID 41787321, 2026).
autism (17 papers, 2011 to 2025). Persistent deficits in social interaction and communication and interaction as well as a markedly restricted repertoire of activity and interest as well as repetitive patterns of behavior. "A correlation with the severity of ASD was also observed, with IL-4 being associated with severe forms of ASD (according to the Autism Diagnostic Surveillance Scheme score) and IL-1β with mild ASD forms." (PMID 39125780, 2024). "IL4, another anti-inflammatory gene, exhibited deficient expression levels in our study cell lines and an almost 80% decreased expression in the astrocytes of patients with autism vs. controls." (PMID 38994948, 2024). "Two such studies examined mid-pregnancy maternal serum cytokine levels, and both identified alterations in serum interleukin (IL)-4 in mothers whose children go on to have autism diagnosed in early life." (PMID 39247132, 2024). "Key cytokines and their receptors investigated in relation to childhood autism include IL-17 A, IL-1β, IL-2R, IL-4, IL-6, and various interleukins, each with diverse cellular origins and target cell types." (PMID 38475688, 2024). "Nevertheless, a prospective cohort study observed that the increased maternal level of Interleukin 4 (IL-4), an anti-inflammatory cytokine, in the 28th week of pregnancy relates to a higher number of childbirths with signs of autism." (PMID 37049390, 2023). "In our well-characterised prospective cohort of autistic children, we confirmed mid-gestational alterations in maternal IL-4 concentrations in autism affected pregnancies versus matched controls." (PMID 34785716, 2021). "Further, there is an elevation of some anti-inflammatory cytokines like Interleukin-4 (IL-4) and interleukin-10 (IL-10) in children with autism." (PMID 33269154, 2020). "In certain subtypes of the autism spectrum there is evidence for increases in blood levels of IL4 and/or IL13." (PMID 29232822, 2017). "IL4, another anti-inflammatory gene with 3-fold higher expression in astrocytes vs. neurons and an overall low level of expression, exhibited 5-fold greater expression in astrocytes of controls vs. patients with autism (i.e., 80% decrease in autism, p = 0.04)." (PMID 38994948, 2024). "In addition, reports consistently delineate unchanged IL-13, IL-10, IL-5, and IL-4 levels in the plasma/serum and post-stimulated blood immune cells in individuals with autism as compared with controls." (PMID 36268027, 2022). "By contrast, elevated concentrations of IL-2, IL-4 and IL-6 were significantly associated with an increased risk of DD without autism." (PMID 21810230, 2011). "The Early markers for Autism study found that high levels of IL-4, IL-5 and interferon-γ (IFN-γ) in maternal serum at 15–19 weeks of gestation were associated with a 50% higher risk of ASD, whereas high levels of IL-2, IL-4 and IL-6 was associated with developmental delay in the absence of ASD." (PMID 35222122, 2022). "They found an imbalance between Th1 and Th2 cytokines with increased IL-4+CD4+ T cells and IL-4+CD8+ T cells and decreased proportions of IFN-γ+CD4+ T cells, IL-2+CD4+ T cells, and IFN-γ+CD8+ and IL-2+CD8+ T cells in children with autism." (PMID 29307081, 2018). "An alternative profile of increased IL-2, IL-4 and IL-6 was more common for women who gave birth to a child subsequently diagnosed with DD without autism." (PMID 21810230, 2011). "The Th1-Th2 paradigm, that is immune skewing toward type-1 cell-mediated immunity (interferon-gamma promoted immunity) vs. type-2 humoral immunity (IL-4, IL-5 and IL-13 promoted immunity), may not be properly applicable to immune alterations in autism." (PMID 21799730, 2011). "Therefore, our findings indicate that increased production of Th1 cytokines (IFN-γ) and Th17 cytokines (IL-17), along with no change in Th2 cytokines (IL-4, IL-5, and IL-13), might suggest a skewing toward the Th1/Th17 phenotype and dampening of the Th2 phenotype in the context of autism." (PMID 36268027, 2022).
endothelial dysfunction (17 papers, 2012 to 2025). In vascular diseases, endothelial dysfunction is a systemic pathological state of the endothelium (the inner lining of blood vessels) and can be broadly defined as an imbalance between vasodilating and vasoconstricting substances produced by (or acting on) the endothelium. "IL-4 and IL-13 are associated with cardiac fibrosis and hypertrophy, while IL-1β mediates inflammation, endothelial dysfunction and myocardial injury." (PMID 39633480, 2024). "Subsequently, they found that IL-4 treatment and IL-4/ interleukin 10 (IL-10) co-treatment was able to significantly reduce blood pressure and prevent endothelial dysfunction in a TLR3-induced PE mouse model." (PMID 32337535, 2020). "However, the exact mechanisms responsible for IL-4 dependent endothelial dysfunction in VEC remained unclear." (PMID 27214384, 2016). "Furthermore, owing to its pleiotropic roles in immune modulation and tissue repair, IL-4 may also have broader therapeutic relevance for other neurovascular disorders characterized by endothelial dysfunction and glial activation." (PMID 40671907, 2025). "Together with VEGF-A, IL-4 may play an important role in endothelial dysfunction in HCAECs." (PMID 36497143, 2022). "For instance, pro-inflammatory metabolites (such as NO-related molecules), cytokines (including IL-1β, TNF-α, IFN-γ, IL-4, IL-5, IL-8, G-CSF, and MIP-1b), and markers of endothelial dysfunction (e.g., homocysteine) were found to be increased in VaD patients." (PMID 32340195, 2020). "Furthermore, studies have demonstrated that 20-HETE stimulates the production of inflammatory cytokines, including IL-8, IL-13, IL-4, and PGE2, in endothelial cells resulting in endothelial cell activation and endothelial dysfunction." (PMID 36238558, 2022). "Based on the current findings, IL-1RA, IL-2, IL-4, IL-6, GM-CSF and IFN-γ were elevated to remarkably high levels in DM-SFTS patients, likely contributing to the fatal outcome, together with the development of depressed immunity and endothelial dysfunction." (PMID 31136581, 2019). "Many cytokines such as TNF-alpha, IL-1, IL-2, IL-4, IL-6, IL-18, monocyte chemoattractant protein-1 (MCP-1), vimentin, and platelet-derived growth factor (PDGF) are produced by macrophages and T lymphocytes activated due to endothelial dysfunction and oxidative stress." (PMID 34349888, 2021). "Th1 response, not counteracted by an increase of anti-inflammatory IL-4 and IL-10 production, may contribute to tissue damage, endothelial dysfunction, and systemic inflammation." (PMID 24324294, 2013).
eosinophilic esophagitis (17 papers, 2014 to 2025). Eosinophilic esophagitis (EoE) is a chronic, allergic disease of the esophagus characterized clinically by symptoms of esophageal dysfunction (including vomiting, dysphagia, feeding disorders, food impaction and abdominal pain) which persist after treatment with proton pump inhibitors (PPIs). "Eosinophilic esophagitis (EoE) is a chronic, Th2-associated inflammatory disorder characterized by pronounced inflammation of the esophagus with cytokines such as Il-5, Il-13, Il-4, and IgE that contribute significantly to the EoE pathogenesis, similarly to AD." (PMID 38256267, 2024). "In eosinophilic esophagitis (EoE), food allergens trigger a T-helper 2 (Th2) immune response with production of Th2 cytokines such as interleukin (IL)-13 and IL-4." (PMID 24988451, 2014). "Dupilumab has demonstrated significant efficacy in eosinophilic esophagitis by reducing eosinophilic inflammation through inhibition of IL-4 and IL-13 signaling pathways, and thus could theoretically exert similar beneficial effects in EoEM." (PMID 40884722, 2025). "Dupilumab is a monoclonal antibody targeting interleukin-4 and interleukin-13, approved for the treatment of multiple T2 diseases and more recently for Eosinophilic Esophagitis (EoE)." (PMID 39906352, 2024). "Notably, in eosinophilic esophagitis (EoE), a type 2 inflammation-driven disorder triggered by food proteins, milk-responsive Tfh cells, which produce IL-10 and low levels of IL-4, support class switch to IgG4 and contribute to distinct clinical manifestations." (PMID 40574856, 2025).